TPPP3 (tubulin polymerization promoting protein family member 3)
Diseases named in the same sentence as TPPP3 in open-access papers (continued):
Sharing a sentence is not in itself a finding about the gene and the disease.
cancer (15 papers, 2012 to 2026). A tumor composed of atypical neoplastic, often pleomorphic cells that invade other tissues. "TPPP3 was first implicated in cancer shortly after its initial discovery." (PMID 41148789, 2025). "Conversely, there are certain cancers where TPPP3 is associated with better survival." (PMID 41148789, 2025). "In addition to Fos, some other genes associatedwith cancer, such as Anxa1, Samd9, Tppp3, Slc22a3, and Ly6d, were differently regulated in both or one of the GX-rich groups,compared with the control group." (PMID 38343302, 2024). "Furthermore, TPPP3 mediates the dynamics and stability of microtubules and is associated with multiple immune-related pathways in various types of cancer." (PMID 36980682, 2023). "Even with all this research assessing the impact of TPPP3 on these different cancers, the question remains—what does TPPP3 do?" (PMID 41148789, 2025). "In cancer, we know that it is involved in proliferation and metastasis, because silencing of TPPP3 results in a decrease in expression of proliferation and metastasis markers, followed by a likewise decrease in proliferative and metastatic potential." (PMID 41148789, 2025). "This would be valuable in not only further characterizing TPPP3 in health and disease, but it would also help in the development of more targeted therapies for these diseases, particularly in cancer." (PMID 41148789, 2025). "TPPP3 appears to be able to regulate EMT in multiple different cancers, but through different mechanisms." (PMID 41148789, 2025). "Independently of the cancer-related potency of TPPP3, the protein is involved in the developmental processes of the musculoskeletal system." (PMID 36230985, 2022). "The fact that the TPPP3 levels are distinct among the various cancers according to different databases/publications highlights the importance of carrying out in vitro and in vivo experiments along with such studies." (PMID 36230985, 2022). "This study provides a comprehensive analysis of TPPP3 expression in cancer databases and its relationship to the prognosis of cancer patients." (PMID 33083464, 2020). "We carried out a pan-cancer analysis of TPPP3, which indicates that TPPP3 has a different expression trend with other tumors in HNSC." (PMID 33083464, 2020). "To more accurately assess TPPP3 expression in human cancers, we used RNA-seq data from 31 malignancies in The Cancer Genome Atlas (TCGA) and Genotype-Tissue Expression (GTEx) to examine the TPPP3 expression." (PMID 33083464, 2020). "However, they did identify TPPP3 as a target of microRNA-1827 which has the potential to be leveraged as a therapeutic option in cancers with aberrant TPPP3 expression." (PMID 41148789, 2025). "Thus far, we have discussed how TPPP3 has a pro-tumorigenic role in multiple different cancer types." (PMID 41148789, 2025). "Surprisingly, recent publications have reported the enrichment of TPPP3 in certain cancers." (PMID 36230985, 2022). "In this article, we first performed a pan-cancer analysis of TPPP3 expression." (PMID 33083464, 2020). "Both of these subtypes shared characteristics of myofibroblast cancer-associated fibroblasts (mCAFs) because of the high level of expression of the genes encoding extracellular matrix building, i.e., COL4A1; ECM remodeling proteins, i.e., MMP11; and contractile proteins, i.e., TPPP3 and MYL9." (PMID 39796089, 2024). "However, TPPP3 may operate through distinct, cancer-type-specific pathways." (PMID 41148789, 2025). "Taken together, these results suggested that hnRNP A2B1 regulated the pre-mRNA splicing of pro-apoptosis genes (DAPK1, SYT7, and RNF128) and anti-apoptosis genes (EIF3H, TPPP3, and DOCK2), thus leading to the suppression of apoptosis of cancer stem cells." (PMID 33509274, 2021).
cancer (continued). "First, we used the SingleR package and the known markers of cancer and alveolar cells to identify a cancer cluster and alveolar cluster; EPCAM and SOX4 were used to mark the cancer cluster; SFTPC and SFTPA1 to mark the alveolar cluster; CAPS and TPPP3 to mark epithelial cells." (PMID 33783985, 2021). "TPPP3 protein is not reported in cancer, but its knockdown suppressed cell proliferation and induced cell cycle arrest in HeLa cells." (PMID 28330331, 2016). "Overexpressed genes in the PP adipose tissue of cancer patients that are involved in cell cycle and proliferation include PLCB1, that modulates cyclin D3 and CDK4 in response to the IGF-1 mitogenic stimulus or TPPP3, that regulates G2-M and G1-S transitions." (PMID 23009291, 2012).
infection (4 papers, 2018 to 2022). The state of being infected such as from the introduction of a foreign agent such as serum, vaccine, antigenic substance or organism. "In contrast, genes associated with ECM organization (Col4a5, Col4a6, Col6a4), microtubule polymerization formation (Tppp, Tppp3), and mitochondrial biogenesis (Ppargc1a) were found to be among the top down-regulated DEGs during infection." (PMID 29339782, 2018). "DHCR24 and TPPP3 genes showed limited to no variance in the infection severity." (PMID 33602138, 2021).
cardiovascular disease (1 paper, 2020). "Interestingly, a recent study identified that TPPP3 is associated with blood pressure which is a common cardiovascular disease, providing suppport for our findings." (PMID 33082910, 2020). "In our study, knockdown of TPPP3 in PA-treated HUVECs could significantly prevent HUVECs from apoptosis and release of ROS, providing a new potential target for treatment of cardiovascular disease." (PMID 33082910, 2020).
neurodegenerative disease (1 paper, 2025). A disorder of the central nervous system characterized by gradual and progressive loss of neural tissue and neurologic function. "TPPP3 has also been explored in the context of neuron regeneration and neurodegenerative diseases." (PMID 41148789, 2025). "Together, these studies indicate that TPPP3 may play a significant role in neuron biology and neurodegenerative disease and further research is needed to further characterize its roles in these cell types." (PMID 41148789, 2025).
TPPP3 also shares sentences with these, for which no sentence is quoted: gastric cancer (2 papers); bladder cancer (1); brain cancer (1); congenital myasthenic syndrome (1); diabetic neuropathy (1); head and neck tumors (1); hypothyroidism (1); kidney cancer (1); kidney chromophobe (1); lung adenocarcinoma (1); lung squamous cell carcinoma (1); myasthenia gravis (1); neurological disorders (1); ovarian clear cell cancer (1); senile cataract (1); small cell lung carcinoma (1); stomach cancer (1).